USP7 (ubiquitin specific peptidase 7)
Diseases named in the same sentence as USP7 in open-access papers (continued):
Sharing a sentence is not in itself a finding about the gene and the disease.
multiple myeloma (continued). "USP7 knockdown overcomes Bortezomib resistance by suppressing the NF-kB signaling pathway in multiple myeloma." (PMID 31730000, 2019). "In 2018, some researchers found that knockout of USP7 dramatically increased the sensitivity of multiple myeloma (MM) cells to bortezomib (BTZ) which led to myeloma cell death and inhibited NF-κB activation by stabilizing IκBα." (PMID 31114498, 2019). "USP7 inhibitors show great efficacy for inhibiting myeloma cell growth and overcoming NEK2-induced and acquired drug resistance in xenograft myeloma mouse models." (PMID 31730000, 2019). "It has been reported that the DNA damage inducer RRx-001 acts synergically with the USP7 inhibitor P5091 in Multiple Myeloma." (PMID 30786932, 2019). "It has been reported that increased levels of USP7 directly correlates with the development of multiple cancers, such as prostate cancer, multiple myeloma, ovarian cancer, etc.." (PMID 30319415, 2018). "USP7 inhibitor P5091 was shown to exhibit impressive properties for the treatment of Multiple Myeloma (MM)." (PMID 28418900, 2017). "The pharmacological inhibition of USP7 has shown antitumor properties in several tumor types, including multiple myeloma, neuroblastoma, colon cancer, and lung neuroendocrine tumors." (PMID 28415632, 2017). "Recent studies have shown that the overexpression of USP7 in prostate cancer correlates with tumor aggressiveness and that the inhibition of USP7 can induce the apoptosis of multiple myeloma (MM) cells resistant to conventional and bortezomib therapies." (PMID 25519684, 2015). "The importance of deubiquitinating enzymes in myeloma pathogenenesis, and their potential as drug targets, was recently demonstrated using an inhibitor targeting USP7, and another targeting UCH-L5 and USP14, two proteasome-associated DUBs." (PMID 26513019, 2015). "Moreover, USP7 plays a crucial role in multiple myeloma resistance development by binding the NIMA-related kinase 2 (NEK2)." (PMID 41157055, 2025). "Up to date, only one report examined the role of USP7 in pDCs and explored whether USP7 affects pDCs maturation and function in multiple myeloma." (PMID 40247205, 2025). "Indeed, USP-7 was found to be highly expressed in a variety of malignant tumors, including myeloma, prostate cancer, hepatocellular cancer, ovarian cancer, and glioma." (PMID 37298148, 2023). "The first USP7 inhibitor, P5091, was previously shown to inhibit multiple myeloma proliferation." (PMID 37762082, 2023). "Interestingly, RRx-001 plus USP7 inhibitor P5091 has been reported to trigger synergistic anti-tumoral activity, in multiple myeloma and different preclinical models." (PMID 30786932, 2019). "Meanwhile, Chauhan and colleagues indicated that the inhibitor of the deubiquitylating enzyme USP7 could induce apoptosis in myeloma cells that are resistant to conventional therapies, including bortezomib, by inhibiting HDM2 and p21." (PMID 29441489, 2018). "CRIP1 enhances proteasome activity and autophagy by binding to the ubiquitin specific peptidase 7 (USP7) and the proteasome activating protein 200 (PA200) in multiple myeloma." (PMID 40118853, 2025). "In multiple myeloma, NEK2 inhibits its own and Beclin1 degradation by binding to ubiquitin-specific protease 7(USP7), thereby activating classical NF-κB signaling and autophagy pathways, promoting disease progression and resistance to bortezomib." (PMID 38503948, 2025). "While losing either RNF4 or USP7 insignificantly increased sensitivity to bortezomib, an FDA-approved therapeutic for multiple myeloma and mantel cell lymphoma, losing both genes rendered cells significantly more sensitive." (PMID 37607592, 2023).
multiple myeloma (continued). "P5091 (inhibitor of USP7) and b-AP15 (inhibitor of USP14/UCHL5) inhibit the growth of bortezomib-resistant multiple myeloma [41,42,]." (PMID 34272356, 2021). "USP7 inhibitors such as p5091, p220077, and p50429 enhance the ubiquitination and degradation of murine double minute 2 (MDM2), thereby inducing apoptosis in bortezomib-resistant multiple myeloma (MM) cells." (PMID 40296903, 2025). "UA might interact with USP7 in RPMI8226 human myeloma cells and could inhibit myeloma cell proliferation (IC50 = 6.56 μmol/L), accompanied by reductions in USP7 substrates such as MDM2, UHRF1, and DNMT1 related to the inhibition of USP7." (PMID 34835969, 2021).
prostate carcinoma (45 papers, 2013 to 2025). A carcinoma that arises from epithelial cells of the prostate gland. "On the other hand, it is widely known that USP7 overexpression in prostate cancer, ovarian cancer and liver cancer is highly associated with tumor metastasis and invasion." (PMID 34812471, 2021). "Collectively, our findings revealed that thepromotion of the malignancy-associated characteristics of prostate cancer cellsby USP7 was in part due to EZH2 stabilization." (PMID 32453339, 2020). "Recently, it has been demonstrated that the stability of the androgen receptor in prostate cancer cells is regulated by the de-ubiquitinase USP7, also known as herpesvirus-associated ubiquitin-specific protease." (PMID 28415632, 2017). "Single nucleotide polymorphisms in Hdm2, HdmX, and USP7 have also been associated with aggressive prostate cancer." (PMID 25605410, 2015). "Therefore, loss of USP7 effectively induced apoptotic cell death in these lung and prostate cancer cells." (PMID 33207738, 2020). "Next, we performed loss-of-function experiments to clarify whether USP7 induces cell death in lung and prostate cancer cell lines." (PMID 33207738, 2020). "While diseases caused by pathogenic somatic mutations of USP7 are rare, the aberrant expression of USP7 is much more frequent, resulting in deregulation of numerous pathways and contributing to disease states that include non-small cell lung cancer and prostate cancer." (PMID 32850836, 2020). "USP7 has been regarded as a promising target of anticancer therapies because itregulates the stability of several proteins associated with cancer progression;findings on the potential of USP7 inhibitors as agents for prostate cancer treatmenthave already been reported." (PMID 32453339, 2020). "For example, in prostate cancer, USP7 is often upregulated, promoting PTEN localization in the cytoplasm and not in the nucleus." (PMID 41157055, 2025). "For example, recent studies demonstrated that USP7 promoted the spread of prostate cancer through an interaction with the 5-dihydrotestosterone-activated androgen receptor." (PMID 41157055, 2025). "Molecular dynamics simulations and biological evaluation techniques were used to determine that USP7 inhibitors had an inhibitory effect on LNCaP in human prostate cancer cells." (PMID 38276639, 2023). "In prostate cancer, USP7 can deubiquitinate and stabilize the androgen receptor in an androgen dependent manner, promoting the androgen receptor binding to chromatin for the transcription of target genes related with cell growth and proliferation." (PMID 36186590, 2022). "In prostate cancer, inhibition of USP7 expression is found to have an anti-proliferative effect on cancer cells." (PMID 34869041, 2021). "USP7 overexpression has been observed in prostate cancer, which is correlated with the increased aggressiveness of the tumors." (PMID 32300595, 2020). "In particular, it has been reported that overexpression of USP7 is closely related to the malignancy of prostate cancer." (PMID 33207738, 2020). "Next, we characterized the physiological function of EZH2protein stabilization by USP7 in prostate cancer." (PMID 32453339, 2020).
prostate carcinoma (continued). "As expected, the levels of USP7 were higher in lung and prostate cancer cells than in normal hTERT-RPE cells." (PMID 33207738, 2020). "In comparison to the clinically relevant MDM2 inhibitors, compound 4 has equal or superior anticancer activity in acute lymphoblastic leukemia cell line RS4;11 and prostate cancer cell line LNCaP, which are hypersensitive to USP7 inhibition." (PMID 32300595, 2020). "The key role of USP7 in theproliferation of prostate cancer cells was identified using USP7 inhibitors andUSP7-knockdown." (PMID 32453339, 2020). "Collectively, these results indicate that the promotion of cellmigration, invasion, and sphere formation by USP7 is partly attributable to thestabilization of EZH2 in prostate cancer cells." (PMID 32453339, 2020). "In prostate cancer, USP7 overexpression has been reported to show a directcorrelation with tumor aggressiveness (Songet al., 2008)." (PMID 32453339, 2020). "In prostate cancer, targetable levels of USP7 and CCDC6 have been detected in a wide series of prostate tumor biopsies via IHC staining." (PMID 31242618, 2019). "USP7 has been identified as an oncogene, and plays a key role in tumorigenesis in several cancer types, including prostate cancer." (PMID 31730000, 2019). "The expression of USP7 increases significantly in high-grade prostate cancer biopsies compared with low-grade biopsies." (PMID 30319415, 2018). "Although the mechanisms leading to the antitumor effect of USP7 inhibitors need to be clarified, the efficacy of USP7 inhibitors can be tested in more tumor types, including prostate carcinoma." (PMID 28415632, 2017). "The P5091 treatment affected the LNCaP cell number, particularly in presence of DHT, suggesting a key role of USP7 in the growth of hormone-sensitive prostate cancer cells." (PMID 28415632, 2017). "We scored and correlated CCDC6 and USP7 expression levels in a prostate cancer tissue microarray (TMA)." (PMID 28415632, 2017). "Here, we correlated the expression levels of CCDC6 and USP7 proteins in primary prostate cancers (PC)." (PMID 28415632, 2017). "Recently, the deubiquitinating enzyme USP7 has been identified as a novel AR co-regulator in prostate cancer cell." (PMID 28415632, 2017). "The involvement of overexpressed USP7 has already been described in prostate cancer via dysregulation of PTEN." (PMID 25605410, 2015). "USP7 is overexpressed in prostate cancer where it drives the deubiquitination and nuclear exclusion of PTEN, which has been correlated with more aggressive disease." (PMID 24123619, 2013). "Therefore, further investigations are necessary to confirm USP7’s involvement in the angiogenetic progression of ovarian and prostate cancer cells and its potential as a therapeutic target." (PMID 41157055, 2025). "For these reasons, USP7 inhibition could decrease prostate cancer cell migration, invasion, and proliferation." (PMID 41157055, 2025). "Furthermore, it has been reported that EZH2 can directly bind to USP7 in prostate cancer cells to stabilize EZH2, thereby promoting metastasis." (PMID 35163710, 2022). "It has been reported that EZH2 recruits USP7 to stabilize EZH2 in prostate cancer cells." (PMID 35163710, 2022). "Moreover, in both epithelial ovarian cancer and prostate cancer, the overexpression of USP7 is found to promote cell invasion, the increased expression level of which is also related to poor survival of ovarian cancer patients." (PMID 34869041, 2021). "Moreover, another research illustrated that USP7 elevates EZH2 stability by mediating EZH2 deubiquitination in prostate cancer cells." (PMID 33308321, 2020). "Thus, wetested the sensitivity of prostate cancer cells to EZH2 inhibitors incombination with the USP7-specific inhibitor P5091." (PMID 32453339, 2020). "In addition, USPs (ubiquitin-specific protease) amplification has been reported in prostate cancer, such as USP2a, USP7, and USP10." (PMID 32784507, 2020).
prostate carcinoma (continued). "Furthermore, the USP7-specific inhibitor P5091 augmented theinhibition of cell migration, invasion, and sphere-forming abilities by EZH2inhibitors in prostate cancer cells." (PMID 32453339, 2020). "In this study we have investigated whether the pharmacological inhibition of USP7, by impairing the stability of AR, is able to weaken the AR-dependent proliferation of prostate cancer cells." (PMID 28415632, 2017). "Thus, the expression of USP7 has been directly correlated to prostate cancer aggressiveness and has been considered a possible target of therapy, in this tumor type." (PMID 28415632, 2017). "Recent studies have reported elevated levels of USP7 in prostate cancer and gliomas." (PMID 27780924, 2016). "A USP7 inhibitor could target prostate cancers; however, the effectiveness of such an inhibitor needs further study." (PMID 25605410, 2015). "The involvement of USP7 in other mechanisms of prostate cancer awaits further investigations." (PMID 25605410, 2015). "Overexpression of USP7 has been associated with increased tumor aggressiveness in human prostate cancer and poor prognosis in lung squamous cell carcinoma and large cell carcinoma, while reduced USP7 expression is linked to adenocarcinoma progression in non-small cell lung cancer." (PMID 40166258, 2025). "Finally, we propose that the assessment of CCDC6 and USP7 tissue expression could provide us with a predictive tool to manage prostate cancer patients at advanced stage." (PMID 28415632, 2017). "USP7 deubiquitinated PLK1 to sustain its protein stability, and then promoted cell proliferation, taxane resistance, and chromosome misalignment in prostate cancer." (PMID 38625581, 2024). "Several substrates contributed to invasion and migration regulated by USP7, such as EZH2 in prostate cancer, and LSD1 in glioblastoma." (PMID 34469054, 2021). "In prostate cancer cells, the transcriptionalrepression function of EZH2 was inhibited by USP7-knockdown." (PMID 32453339, 2020). "Relationships between transcription factors and DUBs can be complex: for example USP7, USP12, USP14, USP22 all appear to regulate the stability and function of androgen receptor (AR) in prostate cancer." (PMID 30854565, 2019). "USP7 promoted the deubiquitination of EZH2, thereby accelerating prostate cancer cell metastasis." (PMID 40329406, 2025). "Moreover, our study presents evidence that USP7 stabilizes the demethylation repair proteins ALKBH2 and ALKBH3 in GBM cells, expanding upon previous observations in prostate cancer cells." (PMID 40835840, 2025). "It has been reported that USP7 deubiquitinates and stabilizes EZH2 in prostate cancer cells." (PMID 35418124, 2022). "Notably, combined treatment with USP7 inhibitor P5091 and EZH2inhibitors (GSK126, EPZ6438, and DZNep) augmented the inhibition of cell migration,invasion, and sphere-forming abilities in prostate cancer cells." (PMID 32453339, 2020). "However, further studies are needed to clarify the differences in thephysiological function and mechanisms of USP7 and USP44 as EZH2 protein stabilizersin prostate cancer." (PMID 32453339, 2020). "Then, CCDC6 and USP7 may be predictive biomarkers for the combined treatment of USP7 and PARP-inhibitors in advanced prostate cancer." (PMID 31242618, 2019). "Here we suggest that the lethal effect obtained by the combined treatment of the PARP inhibitors with the USP7 inhibitors in prostate cancer cells that express CCDC6, and its de-ubiquitinating enzyme USP7, may be considered an “induced synthetic lethality”." (PMID 28415632, 2017).
prostate carcinoma (continued). "Moreover, we tested the efficacy of the USP7 inhibitors, in combination with PARP-inhibitors as a novel therapeutic option in advanced prostate cancer." (PMID 28415632, 2017). "The hormone-sensitive LNCaP prostate cancer cell lines, that show appreciable levels of USP7, were treated with various concentrations of the USP7 inhibitor P5091 or vehicle, with or without DHT stimulation." (PMID 28415632, 2017). "Thus, CCDC6 and USP7 represent predictive markers for the combined treatment of the USP7-inhibitors and PARP-inhibitors in advanced prostate cancer." (PMID 28415632, 2017). "USP7 could also deubiquitinate and stabilize EZH2 in prostate cancer cells." (PMID 36878903, 2023). "However, the role of USP7 in themodulation of EZH2 protein stability in prostate cancer cells has not yet beenelucidated." (PMID 32453339, 2020). "Moreover, combined treatment with the USP7-specific inhibitorP5091 and EZH2 inhibitors, such as GSK126, EPZ6438, and DZNep, inducedsynergistic inhibitory effects on cell migration, invasion, and sphere-formingpotential in prostate cancer cells." (PMID 32453339, 2020). "To evaluate the expression of USP7 in both normal cells and lung and prostate cancer cells, we performed immunoblotting using samples isolated from hTERT-immortalized retinal pigment epithelial (hTERT-RPE) normal cells, NCI-H460 and A549 NSCLC cells, and LNCaP and DU145 prostate cancer cells." (PMID 33207738, 2020). "The inhibition of USP7, able to affect the stability of the AR isoforms but also that of proteins like CCDC6 involved in HR impairment, might be able to sensitize hormone-sensitive and hormone-resistant prostate carcinoma to PARP inhibition." (PMID 31242618, 2019). "Moreover, in these cells, we have investigated whether the inhibition of the deubiquitinase USP7, by lowering the CCDC6 levels and impairing the homologous recombination (HR) processes may increase the prostate cancer cells sensitivity to PARP inhibitors." (PMID 28415632, 2017). "Thus, we decided to test in prostate cancer cells the sensitivity to PARP inhibitors in combination or not with the USP7 inhibitors." (PMID 28415632, 2017). "For this, the study focused on assess three embryonal CNS tumor lineages (DAOY, USP13-MED and USP7-ATRT), as well as three non-CNS tumor cell lines from breast, colorectal and prostate cancer." (PMID 39347716, 2024).